IFITM1 (interferon induced transmembrane protein 1)
Diseases named in the same sentence as IFITM1 in open-access papers (continued):
Sharing a sentence is not in itself a finding about the gene and the disease.
cervical carcinoma (8 papers, 2012 to 2025). A carcinoma arising from either the exocervical squamous epithelium or the endocervical glandular epithelium. "Building on these findings, the authors focused on the cell surface proteome and, for the first time to the best of our knowledge, it was demonstrated how IFITM1 levels impact the cervical cancer cell surfaceome and associated cell phenotype." (PMID 40314078, 2025). "In line to the findings in our ASCC RNAseq cohort, we found a significant association between high expression of IFITM1 and reduced recurrence-free survival in the TCGA cervical cancer dataset." (PMID 38653773, 2024). "Recent evidence showed that high expression of IFITM1 was associated with therapeutically resistant and aggressive disease courses for lung, esophageal and colon cancer, while a protective role was reported in cervical cancer and gastric cancer." (PMID 38653773, 2024). "By contrast, IFITM1 activity is linked to growth suppression in cervical cancers." (PMID 36008984, 2022). "Interestingly, formalin-fixed, paraffin-embedded (FFPE) samples of IFITM1/3-negative cervical cancer were associated with the metastatic potential." (PMID 36466909, 2022). "In the present study, by employing a combination of surface membrane protein isolation and quantitative mass spectrometry, it was comprehensively described how the IFITM1 protein influences the composition of the cervical cancer cell surfaceome." (PMID 40314078, 2025). "Next, we assessed IFITM1 using the TCGA cervical cancer dataset as an example for another HPV-driven squamous cell carcinoma." (PMID 38653773, 2024). "They described a protein–protein interaction between HLA-B and the IFITM1/3 proteins in the SiHa cervical cancer cell line, and IFITM1/3 knockout was shown to lead to HLA-B downregulation." (PMID 36466909, 2022). "In this regard, in our previous work, we identified a distinct subgroup of cervical cancer patients wherein IFITM1/IFITM3 proteins were highly expressed in cervical cancers." (PMID 36008984, 2022). "IFITM1 mRNA expression in 24 cervical cancer tissues was 0.39 ± 0.088, which was significantly lower than that in 15 adjacent normal cervical tissues at 1.295 ± 0.276 (t = − 2.401, P < 0.05)." (PMID 29051711, 2017). "IFITM1 protein expression in chronic cervicitis tissues was higher than that in cervical cancer tissues." (PMID 29051711, 2017). "Our results showed that IFITM1 protein significantly decreased in cervical cancer tissues relative to that in chronic cervicitis tissues." (PMID 29051711, 2017). "IFITM1 mRNA level was significantly lower in cervical cancer tissues than in normal cervical tissues (P < 0.05)." (PMID 29051711, 2017). "The difference in IFITM1 protein expression between samples from chronic cervicitis and cervical carcinoma was statistically significant (P < 0.01)." (PMID 29051711, 2017). "Methylation in the IFITM1 gene promoter was analyzed in cervical cancer tissues and normal cervical tissues by MSP." (PMID 29051711, 2017). "A total of 55 cervical cancer and 40 chronic cervicitis paraffin tissues were cut into triplicate sections to analyze the expression of IFITM1, Ki-67, and PCNA proteins." (PMID 29051711, 2017). "IFITM1 protein expression significantly decreased in cervical cancer tissues than in chronic cervicitis tissues (P < 0.01)." (PMID 29051711, 2017). "To explore the role of IFITM1 in carcinogenesis of cervical cancer, we investigated the expression of IFITM1 gene in cervical squamous cell carcinoma." (PMID 29051711, 2017). "Methylation in the IFITM1 gene promoter in cervical cancer tissues increased significantly compared with that in normal cervical tissues." (PMID 29051711, 2017). "Methylation of the IFITM1 gene promoter was significantly higher in cervical cancer than in normal cervical tissues (P < 0.05)." (PMID 29051711, 2017). "The present study focused on the effect of IFITM1 gene on the carcinogenesis and development of cervical cancer." (PMID 29051711, 2017).
cervical carcinoma (continued). "IFITM1 mRNA level was measured by real-time quantitative RT-PCR in cervical cancer tissues and their adjacent normal tissues." (PMID 29051711, 2017). "Methylation analysis of the IFITM1 gene promoter by MSP revealed 47 samples of IFITM1 gene methylation in 60 cervical cancer tissues and five samples of IFITM1 gene methylation in 60 normal cervical tissues; the difference was statistically significant (P < 0.001)." (PMID 29051711, 2017). "However, IFITM1 gene expression in cervical cancer tissues was lower than that in normal cervical tissues." (PMID 29051711, 2017). "The reason why IFITM1 protein expression decreased in cervical cancer tissues is unclear." (PMID 29051711, 2017). "In addition, the IFITM1 gene promoter in methylated cervical cancer tissues at the mRNA expression level was lower than that of the IFITM1 gene promoter in unmethylated normal cervical tissues." (PMID 29051711, 2017). "In contrast, upregulation of IFITM1 expression has been reported to play a critical role in both the precancerous stage and carcinogenesis in patients with gastric mucosa infected with Helicobacter pylori and cervical cancer." (PMID 25588716, 2015). "Therefore, the expression level of IFITM1 may be changed to improve the status of cervical cancer patients." (PMID 29051711, 2017). "The decrease in IFITM1 protein expression in cervical cancer may lead to cell proliferation." (PMID 29051711, 2017). "In addition, reduced IFITM1 gene expression in cervical cancer tissues may be a result of methylation of the IFITM1 gene promoter, which is a potential target for cervical cancer treatment." (PMID 29051711, 2017). "In the current study, we investigated the expression of IFITM1, Ki-67, and PCNA proteins in cervical cancer tissues and chronic cervicitis tissues." (PMID 29051711, 2017). "To investigate the IFITM1-regulated cancer cell surfaceome, we used the SiHa cervical cancer cell line, which expresses relatively high levels of IFITM1 protein even without IFN stimulation." (PMID 40314078, 2025). "In the present study, it was confirmed that, in addition to HLA-B, IFITM1 regulates a whole set of surface proteins in cervical cancer cells, both with and without dependence on IFNγ." (PMID 40314078, 2025). "It was previously demonstrated that knocking out the IFITM1 and IFITM3 proteins led to the downregulation of HLA-B expression on the surface of cervical cancer cells, suggesting an explanation for the inverse correlation between IFITM1/3 expression and metastasis formation." (PMID 40314078, 2025). "Furthermore, the proteomic and gene expression data are supported by functional studies demonstrating the impact of the IFITM1 and IFITM3 proteins on the adhesive, migratory and invasive capabilities of cervical cancer cells, as well as their interactions with immune cells." (PMID 40314078, 2025).
head and neck squamous cell carcinoma (8 papers, 2011 to 2022). A squamous cell carcinoma that arises from any of the following anatomic sites: lip and oral cavity, nasal cavity, paranasal sinuses, pharynx, larynx, and salivary glands. "Interestingly, head and neck squamous cell carcinomas (HNSCC) are characterized by enhanced expression of IFITM1 with particularly high levels of the protein being expressed at the invasive front of the tumor." (PMID 27835870, 2016). "Surprisingly, however, CD81 supports the growth and metastasis of various cancers and promotes the IFITM1-induced invasion of head and neck squamous cell carcinoma (HNSCC) cells." (PMID 36466909, 2022). "However, a previous study showed that IFITM1 plays an important role during invasion at the early stage of head and neck squamous cell carcinoma (HNSCC) progression, and IFITM1 can be a therapeutic target for HNSCC." (PMID 29051711, 2017). "Additionally, it has been demonstrated that IFITM1 protein expression was observed at the invasive front of early invasive head and neck squamous cell carcinoma (HNSCC) lesions, and higher expression of the protein was detected in invasive HNSCC." (PMID 32668617, 2020).
melanoma (8 papers, 2018 to 2024). A malignant, usually aggressive tumor composed of atypical, neoplastic melanocytes. "Six genes closely associated with the prognosis of melanoma patients, including ADCYAP1R1, GPI, IFITM1, KIR2DL4, LIF and NTS, were elected to fabricate a prognosis model." (PMID 38217549, 2024). "We used mRNA expression of the type I IFN-responsive genes Ly6E, MX1, IFI44L and IFITM1 to determine the pre-treatment type I IFN score in the PBMCs from the melanoma patients in our study." (PMID 38967829, 2024). "In this study, six genes (ADCYAP1R1, GPI, IFITM1, KIR2DL4, LIF, and NTS) were identified as being closely associated with prognosis among a pool of 1793 melanoma-related genes." (PMID 38217549, 2024). "By analyzing the TCGA genomics data of SEL1L3, HAPLN3, BST2, and IFITM1, we found that the gene alteration rates in melanoma were 10% for SEL1L3, 4% for HAPLN3, 0.8% for BST2, and 0.6% for IFITM1, and these alterations were not recurrent." (PMID 33753855, 2021). "Our findings indicate that ADCYAP1R1, GPI, and NTS may contribute to a poor prognosis in melanoma patients, while IFITM1, KIR2DL4, and LIF are more likely to be associated with a better prognosis in individuals with melanoma." (PMID 38217549, 2024). "Obviously, ADCYAP1R1, GPI and NTS might lead to poor prognosis for melanoma patients, while IFITM1, KIR2DL4 and LIF are more likely to improve outcomes." (PMID 38217549, 2024). "The genes in this signature, SEL1L3, HAPLN3, BST2, and IFITM1, may be functionally involved in melanoma progression and immune response." (PMID 33753855, 2021). "In this study, six genes (ADCYAP1R1, GPI, IFITM1, KIR2DL4, LIF, and NTS) that exhibited strong correlation with the prognosis of melanoma patients were identified." (PMID 38217549, 2024). "For the malignant melanoma cells, PMEL, IFITM1, HSPA1A, DUSP1, FOS and TMSB4X are the shared driver genes across three subtypes in S4 File." (PMID 38096269, 2023). "When analyzing the potential biological functions of these proteins in melanoma, we found that silencing SEMA4D or IFITM1 promoted, while silencing KIF20A or GPR87 inhibited the proliferation of melanoma cells in vitro." (PMID 34659201, 2021). "Results from the immunohistochemistry assay revealed that SEMA4D and IFITM1 were down-regulated, while KIF20A and GPR87 were over-expressed in melanoma tissue." (PMID 34659201, 2021). "In specific, the results of our in vitro experiments suggest that SEMA4D and IFITM1 may function as tumor suppressor genes while KIF20A and GPR87 may function as oncogenes in melanoma." (PMID 34659201, 2021). "In this study, we present the first evidence that SEMA4D, IFITM1, KIF20A and GPR87 may possess a prognostic value for melanoma." (PMID 34659201, 2021). "However, four genes, i.e., HPDL, GRIPAP1, GBP2, and TRIM34, have been reported to exhibit prognostic significance with respect to melanoma for the first time, while HAPLN3, CCL8, FCGR2A, and IFITM1 have been reported to relate with the initiation and immune microenvironment of cutaneous melanoma." (PMID 36818162, 2023). "Finally, SEMA4D and IFITM1 may function as tumor suppressor genes, while KIF20A and GPR87 may function as oncogenes in melanoma as revealed from results of in vitro experiments." (PMID 34659201, 2021). "However, a role for IFITM1 in melanoma has never been reported." (PMID 31888295, 2019).
ZIKV infection (8 papers, 2016 to 2025). "The novel interactions of FNDC3B with IFITM3 and SPTA1, ARPC1B and AGTR2 with IFITM1 may shed light on mechanisms of host invasion underlying cytoskeletal re-arrangements that follow Zika virus infection." (PMID 29333229, 2016). "In contrast, IFITM1, which is suggested to inhibit early ZIKV infection, was induced at very low levels by ZIKV while IFITM3, which is reported to prevent ZIKV-induced HeLa cell death, was not induced in ZIKV-infected hBMECs." (PMID 28698279, 2017). "Key ISGs that protect against ZIKV infection (Viperin, ISG15, IFITM1, IFI6) were significantly upregulated compared to control in all three treatments." (PMID 36897927, 2023). "The results showed that ZIKV infection significantly increased OAS2, IFIT3 and IFITM1 levels, and decreased Clorf27, DLG1 and EHBP1 levels." (PMID 32276512, 2020). "Interferon-stimulated genes (ISG) such as MX2, IFIT1, IFIT3, IFITM1, IFI35, and RSAD2 (Viperin) were significantly upregulated after ZIKV infection." (PMID 30781519, 2019). "Recently, it was discovered that two small membrane-associated interferon inducible transmembrane proteins (IFITMs) IFITM1 and IFITM3 play a protective role against ZIKV infection by inhibiting replication of the virus and preventing cell death." (PMID 29333229, 2016). "Recent literature has demonstrated that during ZIKV infection, the production of several types of interferon and ISGs is increased, and that IFITM1 and IFITM3 are involved in inhibiting ZIKV infection during the early stages of pathogenesis." (PMID 29333229, 2016). "Furthermore, several ISGs including IFITM1 and IFITM3 have been reported to inhibit ZIKV infection at the early stage of the viral life cycle." (PMID 32276512, 2020).
head and neck cancer (6 papers, 2016 to 2021). A primary or metastatic malignant neoplasm affecting the head and neck. "Furthermore, in lung and head and neck cancers, the interferon induced transmembrane protein 1 (IFITM1) was shown to enhance in vivo tumor growth and tissue invasion at early stage." (PMID 34571733, 2021). "Additionally, IFITM1 has also been shown to enhance migration and invasion in head and neck cancer cells through activation of matrix metalloproteinase 12 (MMP12) and MMP13, key enzymes involved in the degradation of the basement membrane that allows cells to infiltrate into adjacent tissues." (PMID 26897526, 2016).
lung adenocarcinoma (6 papers, 2020 to 2023). A carcinoma that arises from the lung and is characterized by the presence of malignant glandular epithelial cells. "In small-cell lung cancer, IFITM1 overexpression was found to promote distant metastasis, and in lung adenocarcinoma, IFITM1 expression was found to be significantly associated with increased microvessel density and correlated with patient prognosis." (PMID 37259059, 2023). "IFITM1 is closely correlated with angiogenesis, and it may be a potential biomarker for lung adenocarcinoma patients." (PMID 36591519, 2022). "IFITM1 has been reported to be abnormally expressed in tumor tissues and it is an independent prognostic biomarker for patients with acute myeloid leukemia, lung adenocarcinoma and gallbladder cancer." (PMID 34659201, 2021).
non-small cell lung carcinoma (6 papers, 2012 to 2023). A group of at least three distinct histological types of lung cancer, including non-small cell squamous cell carcinoma, adenocarcinoma, and large cell carcinoma. "Several studies showed that IFITM1 critically regulates epidermal growth factor receptor-mediated signaling in non-small cell lung cancer models and is associated with a poor prognosis of patients with adenocarcinoma." (PMID 33585210, 2020). "It was reported that LINC00847 promotes non-small cell lung cancer progression by targeting the miR-147a/IFITM1 axis." (PMID 36864364, 2023). "LINC00847 induces by E2F1 facilitates non-small cell lung cancer progression by targeting the miR-147a/IFITM1 axis." (PMID 36864364, 2023). "Intriguingly, we find that Ifitm1, respectively, the human protein IFITM1 are selectively expressed in the bronchial epithelia of mouse and human lung tissue and that IFITM1 is highly overexpressed in human non-small cell lung cancers (NSCLC)." (PMID 23115618, 2012).
ovarian carcinoma (6 papers, 2020 to 2025). A malignant neoplasm originating from the surface ovarian epithelium. "For instance, miR-147a represses the growth and metastasis of NSCLC via targeting IFITM1 and the progression of epithelial ovarian cancer through the down-regulation of CDK6 protein." (PMID 35196205, 2022). "Particularly, more and more studies have confirmed that IFITM1 is overexpressed in numerous human cancers during the last decade, such as lung, gastric, colorectal, and ovarian cancers." (PMID 33869009, 2021). "IFITM1 (interferon-induced transmembrane protein 1) is an immune response-related protein whose epigenetically regulated overexpression promotes migration, invasion, and metastasis in ovarian cancer, and methylation of the IFITM1 promoter may be a biomarker of progression." (PMID 41373846, 2025).
gallbladder carcinoma (5 papers, 2021 to 2024). "IFITM1 expression is a biomarker for the diagnosis, poor prognosis, and clinical severity of gallbladder carcinomas." (PMID 36591519, 2022). "IFITM1 does not seem to be a specific marker, as it is reported to be highly expressed in several mostly epithelial tumors such as colorectal, gastric, esophageal, and gallbladder carcinoma, in which it represents an independent prognostic biomarker." (PMID 36707859, 2023).